PPP6C (protein phosphatase 6 catalytic subunit)
Diseases named in the same sentence as PPP6C in open-access papers (continued):
Sharing a sentence is not in itself a finding about the gene and the disease.
Hypertension (1 paper, 2022). The presence of chronic increased pressure in the systemic arterial system. "Furthermore, the opposite phenotypes were observed in mice with Treg-specific deletion of protein phosphatase 6c (Ppp6c), a direct target of miR-31, suggesting that Ppp6c had potential to improve Ang II-induced hypertension." (PMID 36009402, 2022).
male infertility (1 paper, 2021). The inability of the male to effect fertilization of an ovum after a specified period of unprotected intercourse. "Finally, PPP6C depletion causes male infertility and the loss of germ cells." (PMID 34580275, 2021).
malignant mesothelioma (1 paper, 2015). A malignant neoplasm of the pleura or peritoneum, arising from mesothelial cells. "We further noted downregulation of protein phosphatase 6 catalytic subunit (PPP6C), whose encoding protein is significantly correlated with malignant mesothelioma proliferation and also previously validated as a direct target of miRNA-31." (PMID 26379276, 2015).
pancreatic adenocarcinoma (1 paper, 2021). "Our study demonstrated that the mRNA expression of PPP6C was higher in pancreatic adenocarcinoma than in normal tissues in the GEPIA dataset." (PMID 33270085, 2021).
Pleural effusion (1 paper, 2023). The presence of an excessive amount of fluid in the pleural cavity. "Indeed, at progression, PPP6C p.H151Y, not detected at T0 and T1, showed an allele frequency of 0.8% and 72.6% in plasma and pleural effusion, respectively." (PMID 37569660, 2023).
prostate adenocarcinoma (1 paper, 2025). "It was determined that 21 proteins (DHX9, EIF5, HPRT1, INPP5B, MCM6, PPP6C, SYF2, etc.)whose expression was increased in PC3‐R cells based on label‐free nLC‐MS/MS analysis were consistent with both TCGA prostate adenocarcinoma N0 and N1 nodal metastasis status and correlation data." (PMID 39799471, 2025).
retinoblastoma (1 paper, 2015). A malignant tumor that originates in the nuclear layer of the retina. "We did not detect significant changes in cell proliferation following reduction of PPP6C or STK40 in either retinoblastoma cell line." (PMID 26379276, 2015). "To improve our understanding of miRNA-31 and/or -200a mediated regulation in retinoblastoma cells, we also evaluated the extent of repression of STK40, PPP6C, and DLL3 in Weri1 cells to determine if these miRNA-mRNA interactions remained intact." (PMID 26379276, 2015). "Furthermore, our work is the first to demonstrate that overexpression of miRNA-31 and/or miR-200a results in differential gene expression patterns of ACOT7, DLL3, PPP6C, and STK40 between two phenotypically different retinoblastoma cell lines." (PMID 26379276, 2015).
skin basal cell carcinoma (1 paper, 2020). The most frequently seen skin cancer. "Dys-regulated PP6 activity plays a role in melanoma development and PPP6C is a somatic driver gene in skin basal cell carcinoma." (PMID 32474700, 2020).
squamous cell carcinoma in situ (1 paper, 2021). "Mice of K and KP genotypes developed squamous cell carcinoma in situ in the tongue approximately 2 weeks after the induction of Ppp6c deficiency and was euthanized due to 20% loss of body weight." (PMID 34145991, 2021). "Mice of K and KP genotypes developed squamous cell carcinoma in situ in the tongue approximately 2 weeks after the induction of Ppp6c deficiency." (PMID 34145991, 2021).
systemic inflammatory response syndrome (1 paper, 2022). SIRS is a serious condition related to systemic inflammation, organ dysfunction, and organ failure. "We utilized a TNF-SIRS mouse model to determine whether PPP6C regulates the onset of systemic inflammatory response syndrome." (PMID 35842423, 2022).
tongue cancer (1 paper, 2021). A malignant neoplasm affecting the tongue. "Chronic inflammation reportedly promotes tumor progression in mice and humans, and our findings strongly suggest that inflammation driven by Ppp6c deficiency in the presence of oncogenic RAS is a factor in tongue carcinoma." (PMID 34145991, 2021).
tongue tumor (1 paper, 2021).
cancer (23 papers, 2013 to 2026). A tumor composed of atypical neoplastic, often pleomorphic cells that invade other tissues. "In the present study, we generated cultured MEFs expressing oncogenic K‐Ras (K‐RasG12V) and analyzed the effect of Ppp6c deficiency to determine how Ppp6c is involved in oncogenic Ras‐induced cancer cell proliferation." (PMID 38318686, 2024). "Previously, we demonstrated that cells with perturbed PPP6C or cancer-associated loss of function mutants in PPP6C show chromosome instability, leading to the formation of aberrant nuclei and micronuclei with damaged DNA." (PMID 36897279, 2023). "This regulation of Aurora A is necessary for proper spindle assembly, and cancer-associated loss of function driver mutations in PPP6C, the catalytic subunit of PP6, leads to micronucleation due to defective chromosome segregation." (PMID 36897279, 2023). "Here, we have used CRISPR genomics to identify the Aurora A activator TPX2 and kinetochore protein NDC80 as key components explaining the cancer-associated PPP6C loss-of-function phenotype." (PMID 36897279, 2023). "A high frequency of mutations significantly associated with BCC tumorigenesis was observed in two cancer-related genes, PPP6C and STK19, in a recent study, including a large cohort of tumors." (PMID 29165358, 2017). "On the other hand, in Drosophila and mice, Ppp6c suppresses the effects of oncogenic Ras (RasV12 in Drosophila and K‐RasG12D in mice), and loss of Ppp6c in concert with oncogenic Ras expression accelerates cancer cell growth." (PMID 38318686, 2024). "We further analyzed PPP6C mutation data from 48,000 tumors across 184 pan-cancer studies." (PMID 35368039, 2022). "We extracted the results for PPP6C, which showed that most cancer cells require PPP6C for proper proliferation." (PMID 38318686, 2024). "Collectively, these findings show that Ppp6c is indispensable for proper proliferation even of cancer cells." (PMID 38318686, 2024). "Overexpression of circCUL2 could inhibit cancer progression via targeting the miR-208a-3p/PPP6C signal pathway." (PMID 35027503, 2022). "These include known factors such as IDH1, as well as previously unreported genes, including four cancer driver genes (FGFR3, PPP6C, MAX, GNAQ)." (PMID 34944895, 2021). "Known cancer drivers NOTCH1, PPP6C, RAC1, EIF4G1, PIK3CA showed significant increase in frequency of SCNA in transition from PPOLs to HNSCC that correlated with their expression." (PMID 31427592, 2019). "Moreover, several confirmed gender-related carcinogenic genes exhibit completely different distributions in male and female cancer samples, such as PIK3CA, NF1, EIF1AY, IGF1R, NRAS, KDM5D, UTY, and PPP6C." (PMID 39541191, 2024). "Although the interaction relationships between hsa-miR-224 and PRPF4B, as well as between hsa-miR-31 and NR3C2/PPP6C have not been experimentally demonstrated previously, the function studies on these target genes in cancers may indirectly reveal the possible roles of hsa-miR-224 and hsa-miR-31." (PMID 33282547, 2020).
tumor (14 papers, 2009 to 2024). "It is unclear how oncogenic K‐Ras expression overcomes cell proliferation failure induced by Ppp6c deficiency; therefore, we sought to shed light on how oncogenic K‐Ras modulates tumor cell growth." (PMID 38318686, 2024). "It is unclear how oncogenic K‐Ras overcomes cell proliferation failure induced by Ppp6c deficiency; therefore, in this study, we attempted to shed light on how oncogenic K‐Ras modulates tumor cell growth." (PMID 38318686, 2024). "Contrary to our expectations, loss of Ppp6c decreased proliferation, anchorage‐independent growth in soft agar, and tumor formation of oncogenic Ras‐expressing mouse embryonic fibroblasts (MEFs)." (PMID 38318686, 2024). "Among these predicted target genes, PPP6C, associated with cell cycle and tumor formation/progression, was selected as a potential target of miR-20a-5p for further analysis." (PMID 34587164, 2021). "The PPP6C gene is mutated in 7.1% of CM cells, with similar prevalence in the different stages of tumor progression (6.3% in primary and 7.4% in metastatic melanoma)." (PMID 30218391, 2018). "In our study, oncogenic K‐Ras‐expressing and Ppp6c‐deficient cells were surrounded by normal wild‐type cells; therefore, cell competition activity of surrounding normal cells may have prevented tumor growth." (PMID 38318686, 2024). "On the other hand, in a previous study using mice, Ppp6c deficiency was also induced in cells surrounding tumor‐forming cells, suggesting that Ppp6c deficiency suppresses cell competition, which increases growth of oncogenic K‐Ras‐expressing and Ppp6c‐deficient cells." (PMID 38318686, 2024). "Although loss of Ppp6c was expected to promote proliferation of K‐RasG12V‐expressing MEFs, it markedly inhibited proliferation of these cells under normal culture conditions, their colony formation on soft agar medium, and their tumor formation upon subcutaneous implantation into C57BL/6 mice." (PMID 38318686, 2024). "Thus it suggests that partial inhibition of CDC42 could be enough to cause a lethal condition in those tumor cells where an amorphic mutation for PPP6C exists." (PMID 20015360, 2009). "Apart from the roles of PP6 in regulating the cell cycle and mitosis, little is understood about how Ppp6c modulates tumor growth." (PMID 38318686, 2024). "Meanwhile, IHC assay results observed the down-regulated expression level of PPP6C in CRC tumor tissues." (PMID 35027503, 2022). "For instance, circCUL2 acts as a sponge for miR-208a-3p to inhibit tumor proliferation via upregulating protein phosphatase 6 catalytic subunit (PPP6C), which induces autophagy in SW480 and SW620 human CRC cells and the SW480 xenograft model." (PMID 36172152, 2022). "The PPP6C protein deficiency is able to induce cutaneous tumorigenesis in mice treated with the DMBA carcinogen, strongly suggesting a role as tumor suppressor gene." (PMID 30218391, 2018). "Consistently, keratinocyte-specific deletion of Ppp6c promotes tumor formation in mice." (PMID 34853298, 2021). "Interestingly, PPP6C has been reported to be involved in both homology-directed repair of DNA double-strand breaks and tumor developments." (PMID 32474700, 2020). "Accumulating pathological evidence suggests that Ppp6c may function as a tumor suppressor." (PMID 34145991, 2021). "RT-PCR assay performed the negative relationship between miR-208a-3p and PPP6C in CRC tumor tissues." (PMID 35027503, 2022). "In addition, recent work shows that downregulation of PPP6C in some (but not all) human tumor cell lines activates ERK." (PMID 38318686, 2024). "In addition to LATS2, many other tumor suppressors such as PPP6C, DKK1, TNFAIP1 and TP53INP1 are also verified as direct targets of miR-373, implying that miR-373 promotes cell proliferation and tumor growth under certain conditions." (PMID 25990556, 2015).
infection (3 papers, 2020 to 2022). The state of being infected such as from the introduction of a foreign agent such as serum, vaccine, antigenic substance or organism. "Moreover, PPP6C depletion also enhanced KSHV primary infection-induced IFN-β mRNA induction and phosphorylation of TBK1 and IRF3 in EA.hy926 cells compared to those in control cells." (PMID 32753499, 2020). "Similarly, one study reported that shRNA-mediated PPP6C knockdown in HepG2 cells has little influence on proliferation rate, but another research showed that in vivo infection of lentivirus shRNA targeting Ppp6c in epidermis leads to an enhanced proliferation of keratinocyte." (PMID 35842423, 2022). "In this study, we demonstrate that dephosphorylation of a catalytic serine residue of cGAS by the phosphatase PPP6C impairs its substrate binding and enzymatic activity, therefore provides a mechanism for keeping the DNA sensor cGAS inactive in the absence of infection to avoid autoimmune response." (PMID 32474700, 2020). "Our findings suggest that PPP6C-mediated dephosphorylation of cGAS impairs its substrate binding activity and innate immune response, which is important to keep cGAS inactive in the absence of infection to avoid autoimmune responses." (PMID 32474700, 2020). "Our findings suggest that PPP6C-mediated dephosphorylation of a catalytic pocket serine residue of cGAS impairs its substrate binding activity and innate immune response, which provides a mechanism for keeping the DNA sensor cGAS inactive in the absence of infection to avoid autoimmune response." (PMID 32474700, 2020).
PPP6C also shares sentences with these, for which no sentence is quoted: acute myelogenous leukemia (2 papers); anaplastic large cell lymphoma (1); B-cell lymphoma (1); basal cell carcinoma (1); colorectal adenocarcinoma (1); colorectal cancer (1); dementia (1); endothelial dysfunction (1); familial melanoma (1); gastric cancer (1); glioblastoma (1); left ventricular hypertrophy (1); liver cancer (1); lung carcinoma (1); lung squamous cell carcinoma (1); medulloblastoma (1); metastatic melanoma (1); metastatic tumors (1); mucosal (1); premature ovarian failure (1); psychiatric disorder (1); schizophrenia (1); thyroid cancer (1).